MSI1 (musashi RNA binding protein 1)
Diseases named in the same sentence as MSI1 in open-access papers (continued):
Sharing a sentence is not in itself a finding about the gene and the disease.
cancer (99 papers, 2006 to 2025). A tumor composed of atypical neoplastic, often pleomorphic cells that invade other tissues. "Comparative integrative multi-omic analyses of these large datasets reveal cancer-selective MSI1-bound targets sharing multiple MYC associated pathways, providing a valuable resource for context-specific therapeutic targeting of G3 MB." (PMID 36473869, 2022). "This identified a strong conservation of KEGG pathways comprising genes characterized by positive association with MSI1 expression in cancer." (PMID 34062997, 2021). "A solid causal relationship between miR-671-5p and MSI1 expression was demonstrated in a panel of GBM cancer cell lines." (PMID 35052701, 2021). "In support of protein–centered studies in these cancer entities, elevated expression of MSI1 is associated with an unfavorable prognosis in these malignancies, as well." (PMID 34062997, 2021). "In agreement, MSI1 was shown to modulate cancer hallmark pathways, including cell cycle control, Hedgehog and AKT signaling." (PMID 34062997, 2021). "The functional impact of MSI1 in cancer was studied on the basis of loss– as well as gain–of function studies, including shRNA–, siRNA–, morpholino–directed impairment of MSI1 abundance and its overexpression." (PMID 34062997, 2021). "By controlling target mRNA turnover and translation, MSI1 is implicated in the regulation of cancer hallmarks such as cell cycle or Notch signaling." (PMID 34062997, 2021). "KEGG: Wnt (38%), Notch (27%) and Hedgehog (17%) signaling pathways were associated with MSI1 expression; however, the conservation between cancer entities is substantially less stringent." (PMID 34062997, 2021). "Despite variable significance of survival analyses on mRNA basis by KM plotter, a strong association of elevated MSI1 protein expression and adverse patient outcome was reported for all these cancers." (PMID 34062997, 2021). "We found that MSI-1 downregulation results in a loss of clonogenic ability of MCF-7 cancer cells after irradiation." (PMID 34291358, 2021). "As for other cancers, such as prostate or esophageal carcinomas, MSI1 depletion was associated with an arrest in the G1 phase accompanied by a de–regulation of CDKN1A (p21/WAF) and NUMB." (PMID 34062997, 2021). "Consistently with its high expression in cancers, and its importance in stem cell signaling, MSI1 has been implicated in CSC properties of different tumors, including GBM." (PMID 33317545, 2020). "Up-regulation of MSI1 in cancers appears to associate with elevated Notch/Wnt signaling, as MSI1 targets Numb and APC (adenomatous polyposis coli) are negative regulators of Notch and Wnt signaling, respectively." (PMID 30097032, 2018). "It has been established that MSI1 is a cancer stem cell marker and its expression is closely associated with stem cell proliferative and differential status." (PMID 29689047, 2018). "Elevated MSI1 levels in a variety of human cancer are associated with up-regulation of Notch/Wnt signaling." (PMID 30097032, 2018). "Although MSI1 expression has been hinted as a prognosis factor in various cancers, the underlying mechanism involved in drug resistance is still an open question." (PMID 27285760, 2016). "Examining genome sequencing data from matched tumor-control pairs across nine diversecancer types, we found that Msi1 and Msi2 were notsignificantly mutated in most of these cancers." (PMID 25380226, 2014). "However, proliferative function was not entirely returned to normal, pointing to additional factors and Musashi-related pathways that are likely involved in anti-proliferative signaling, such as loss of cancer stem cell characteristics after Msi-1 knockdown." (PMID 35619161, 2022). "In any case, whether directly or indirectly, our findings support that MSI-1 loss affects a broad segment of cancer cells and is likely not limited to cancer stem cells." (PMID 34291358, 2021).
cancer (continued). "We revisit MSI1′s expression in a set of solid cancers, describe mechanistic details and implications in MSI1 associated cancer hallmark pathways and highlight current research in drug development identifying the first MSI1–directed inhibitors with anti–tumor activity." (PMID 34062997, 2021). "However, most genes with significant positive association with MSI1 in cancer serve functions, primarily at G1/S transition (red)." (PMID 34062997, 2021). "For KEGG: Cell_cycle and KEGG: Basal_cell_carcinoma, we found the highest conservation with significant associations in 11 out of 18 (61%) of analyzed cancer entities and 100% or 75% conservation among the top four MSI1 de–regulated cancers LGG, GBM, OV and UCEC." (PMID 34062997, 2021). "Increased Msi1 expression might also be linked to tumor initiation since its expression is required for the survival of cancer stem cells, maintenance of the stem cell signature, and promotion of oncogenic activation and cell cycle progression." (PMID 33804958, 2021). "Multiple studies, including the present work, suggest that MSI-1 may be a marker of cancer stem cells and/or linked to cancer stem cell maintenance." (PMID 34291358, 2021). "Msi1 is a member of a family of more than 800 RNA-binding proteins that regulate a multitude of processes associated with the post-transcriptional regulation of gene expression, and when aberrantly expressed can lead to diseases such as cancer." (PMID 23715514, 2013). "Msi1 regulated expression of a set of genes with a well-established role in cell proliferation, cell differentiation and survival and its loss appeared to have a detrimental effect on the maintenance of cancer cells." (PMID 18826648, 2008). "Our data suggested that Msi1 may promote cancer cell proliferation and survival as its loss seems to have a detrimental effect in the maintenance of medulloblastoma cancer cells." (PMID 18826648, 2008). "Cancer is characterized by changes in cell symmetry and self-renewal capacity and therefore it comes as no surprise that genes regulating these processes in normal neural development (i.e., MSI1) may be implicated in developmental brain tumors such as MB." (PMID 36473869, 2022). "In addition, MSI1 is associated with many malignant neoplasms in humans." (PMID 34073088, 2021). "MSI1 plays a pivotal role in stem cell and cancer stem cell (CSC) proliferation, operating through both the Wnt and Notch signaling pathways." (PMID 40271197, 2025). "Due to its regulatory functions, any alteration of the level of expression of MSI-1 often leads to a disruption of signalling pathways, leading to several diseases, including cancer." (PMID 40795964, 2025). "This highlights the importance of MSI-1 and remarks on its potential to be a marker and a promising therapeutic target in cancer disease." (PMID 40795964, 2025). "The compound was tested for its ability to inhibit viability of various cancer cell lines, but also those with low MSI1 expression were affected, possibly indicating that the mode of action is not selective for MSI1." (PMID 39668490, 2024). "In a follow up study, MSI-1 silencing restricted cancer cell proliferation and sensitized cells to irradiation in Ishikawa (EC type 1) and KLE (type 2) cells." (PMID 37620963, 2023). "MSI1, as a suggested oncogene and stem cell marker, has shown an increased expression in many cancer types." (PMID 37607966, 2023). "MSI-1 enhances therapeutic resistance by increasing the expression of DNA repair-associated proteins DNA-PKcs and EGFR, and therefore cancer treatment, in a way that identifies potential inhibitors of MSI proteins using high-throughput analysis." (PMID 37631029, 2023). "RNA-binding protein Musashi1 (MSI1) shows an increased expression level in several cancers and has been introduced as a prognostic marker in some malignancies." (PMID 37607966, 2023). "MSI1 knockdown in glioblastoma and medulloblastoma cells resulted in reduced self-renewal and survival of the cancer cells." (PMID 37607966, 2023).
cancer (continued). "MSI1 is characterized as an RNA-banding protein (RBP) by repressing the mRNA translation and is associated with cancer stem cell properties of various cancers." (PMID 37675218, 2023). "The group also suggested that MSI-1 inhibits cancer cell apoptosis and therefore promotes tumor formation in vitro and in vivo." (PMID 37620963, 2023). "Previous studies by our group showed Msi-1 to be overexpressed in EC, especially in cancer stem cells (CSC) and also linked Msi-1 to Notch-1 expression." (PMID 35619161, 2022). "Among the top 50 genes (most significantly and synergistically downregulated by JQ1 and panobinostat combination), we identified SYK and MSI1 genes as the most cancer relevant genes, particularly considering their involvement in neurodevelopment." (PMID 36357906, 2022). "Among these, we identified SYK (spleen tyrosine kinase) and MSI1 (Musashi1) as the most cancer-relevant genes." (PMID 36357906, 2022). "MSI1, an RNA-binding protein, has been found to regulate multiple critical biological processes that are relevant to cancer initiation and progression." (PMID 36291177, 2022). "In vitro and in patient database analyses, we demonstrate that low Msi-1 is linked to a decrease in Notch-1, DNA-PKcs and TERT, all related to cancer stem cells and therapy resistance, and an increase in p21, an anti-proliferative marker." (PMID 35619161, 2022). "We also found a lower level of promoter methylation in cancer tissues, another indicator of increased Msi-1 expression." (PMID 35619161, 2022). "Increasing reports have indicated that expression of Musashi 1 (MSI1) is tightly correlated to high grade of cancers as well as enrichment of cancer stem cells." (PMID 35158774, 2022). "Over the last decade, MSI1 has emerged as an oncogenic protein that functions as a stem cell determinant to promote cancer cell survival, tumor progression, and its expression is closely correlated to drug resistance and cancer relapse in patients." (PMID 35158774, 2022). "Our general finding that Msi-1 knockdown sensitizes cancer cells to therapy and limits proliferation indicates therapeutic potential." (PMID 35619161, 2022). "MSI1 was also shown to promote tumor progression as the silencing of MSI1 hampered cancer cell proliferation and apoptosis inhibition." (PMID 35158774, 2022). "These pronounced tumor suppression effects exerted by synthetic Pep#11/Pep#26 were likely attributed to the blockade of the oncogenic functions of the endogenous MSI1/AGO2 complex in cancer cells." (PMID 35158774, 2022). "In all other cancer entities investigated, the MSI1 mRNA is barely expressed and/or remains unchanged in tumor vs. normal tissue." (PMID 34062997, 2021). "Msi-1 expression is upregulated in a variety of cancers and promotes tumor development, due to its ability to control the expression of specific cancer-related factors (e.g., oncotachykinin)." (PMID 34502337, 2021). "They help expand the relevance of the radiosensitizing effect and establish MSI-1 as a potential target for improved radiotherapy-based cancer cell eradication." (PMID 34291358, 2021). "We previously demonstrated that the cancer stem cell marker Musashi-1 (MSI1) is an RNA binding protein that promotes radioresistance by increasing downstream RNA stability." (PMID 35052701, 2021). "The oncofetal expression of MSI1 in some cancers and its role in development as well as stem cell fate suggested MSI1 as a promising candidate target in cancer therapy." (PMID 34062997, 2021). "In particular, it is found that MSI1 expression is correlated with malignant tumor development and poor prognosis." (PMID 33882945, 2021). "From our results, we first identified the roles and underlying mechanisms of MSI1 and miR-671-5p in GBM, which regulate radioresistance by STAT3 inhibition and cancer migration and CSC function by TRAF2 suppression." (PMID 35052701, 2021).
cancer (continued). "Due to its specific expression pattern with high levels during development and in a variety of cancers, MSI1 evolved as an interesting target for cancer therapy." (PMID 34062997, 2021). "In contrast to MSI2, for which oncogenic potential and expression was predominantly reported in leukemia, MSI1 expression was shown in a variety of human cancers, primarily solid cancers." (PMID 34062997, 2021). "The high expression of Msi1 is prevalent in Group 4 and correlates with poor prognosis while its knockdown disrupted cancer-relevant phenotypes." (PMID 35011618, 2021). "In this review, we summarize previous findings from development of other organisms, outline MSI1′s expression and function in different cancer entities and highlight the development of MSI1–directed inhibitors." (PMID 34062997, 2021). "There are different factors that regulate MSI1 expression in various cancer tissues including microRNAs which are considered as one of the most important of these factors." (PMID 33541259, 2021). "MSI1 participates in the PKR/eIF2 cancer stem cell-enhancing machinery and promotes proliferation (Chen H.-Y." (PMID 34604242, 2021). "Prospectively, studies on MSI1′s role in translational regulation in cancer cells needs to consider this dual function and external guidance cues, requiring further in–depth investigation." (PMID 34062997, 2021). "By lowering MSI1 expression in spheroid culture, cancer stem cell proliferation is inhibited, as is the expression of Notch1 and cancer stem cell markers such as Oct4, Sox2, and c-Myc." (PMID 34587981, 2021). "The growth of cancer–derived xenografts from colon was diminished by MSI1–directed siRNA application." (PMID 34062997, 2021). "Due to its specific expression pattern and diverse functions, MSI1 represents an interesting target for cancer therapy in the future." (PMID 34062997, 2021). "Results showed that circ_0055625 expression was upregulated, and MSI1 expression was also visibly increased in colony cancer tissues as well as SW480 and SW620 cells compared with normal tissues and FHC cells." (PMID 33882945, 2021). "Previous genomic studies from our group and others determined that Msi1 regulates hundreds of targets through post-transcriptional mechanisms, affecting numerous cancer pathways, such as NUMB/Notch, PTEN/mTOR, TGFβ/SMAD3, MYC, cMET, and others." (PMID 35011618, 2021). "As a post–transcriptional regulator of gene expression, MSI1 controls mRNA turnover and translation of target transcripts, modulating a variety of signaling pathways during development and cancer progression." (PMID 34062997, 2021). "The aim of this review is summarizing the role of MSI1 in stem cell proliferation and cancer promotion." (PMID 32448364, 2020). "Reduction of MSI1 diminishes cancer cell proliferation and activates Caspase 3-mediated apoptosis in colon adenocarcinoma xenografted mouse models." (PMID 32967226, 2020). "Musashi-2 (MSI2) shares a high degree of sequence identity to MSI1, functions redundantly in certain tissues, and is also overexpressed in many cancers." (PMID 32784494, 2020). "Overexpression of MSI1 has been observed in treated cancer cells with chemotherapy drugs and radiotherapy." (PMID 32448364, 2020). "In cervical cancer, MSI1 expression increases cancer cell proliferation through regulation of the cell cycle." (PMID 32448364, 2020). "Although the roles of MSI1 in different cancers extensively correlated with proliferation of cancer cells, its role in cancer cell migration and invasion proffers a much broader role." (PMID 32448364, 2020). "To test the therapeutic potent of MSI1 C-terminus, we launched an in vivo study in which cancer cells were implanted on each flank of the mice subsequently subjected to an intratumoral transfection of Flag control or Flag-C-term." (PMID 31903115, 2020). "It is demonstrated that MSI1 expression increases proliferation of cancer cells in different type of cancers." (PMID 32448364, 2020).
cancer (continued). "MSI1 as a tumor suppressor declines the growth of human colon cancer xenograft and inhibits colony formation by cancer cells." (PMID 32448364, 2020). "In this review, we discuss the functional aspects of MSI1 in stem cell biology and cancer development." (PMID 32448364, 2020). "On the other hand, MSI1 knockdown decreases proliferation of cancer stem cells and induces apoptosis in solid tumors." (PMID 32448364, 2020). "In our study, we identify the MSI1/AGO2 interaction by proteomic analysis from immunoprecipitation in cancer cells." (PMID 31903115, 2020). "Like Musashi‐1 (MSI1), it is overexpressed in a variety of cancers and is a promising therapeutic target." (PMID 31603583, 2020). "By reduction of MSI1 expression in spheroid culture, proliferation of cancer stem cells decreases through reduction of Notch1 and cancer stem cell markers such as Oct4, Sox2, and c-Myc." (PMID 32448364, 2020). "Cytosolic MSI1 enhances tumor proliferation and cancer cell survival through this AGO2-dependent mRNA regulation." (PMID 31903115, 2020). "Due to the main role of MSI1 in metastasis and cancer development, MSI1 would be an appropriate candidate for cancer therapy." (PMID 32448364, 2020). "MSI1 controls the proliferation of cancer stem cells by modulating the Notch and Wnt pathways, as well as Akt signaling pathway." (PMID 32448364, 2020). "Chemotherapy is vital for improvement of clinical outcome in cancer patients; however, different studies have shown that MSI1 contributes to chemoresistance in cancer therapy." (PMID 32448364, 2020). "Knocking down MSI1 reduces tumor progression in several cancer models and overexpressing MSI1 in a rat intestinal crypt-derived cell line induces tumorigenesis in a mouse xenograft model." (PMID 32784494, 2020). "Cytosolic MSI1 enhances tumor proliferation and cancer cell survival, and highly correlates relapse occurrence in patients with GBM and PDAC." (PMID 31903115, 2020). "How microRNAs can perform their functional roles in control of diverse cancers progression through regulation of MSI1 expression will be discussed." (PMID 32448364, 2020). "Downregulation of MSI1 inhibits proliferation of cancer stem cells and reduces the growth of solid tumors in several cancers." (PMID 32448364, 2020). "MSI1 regulates the Wnt and Notch signaling pathways; small molecule inhibitors targeting MSI1 have been investigated as blockers of cancer cell growth." (PMID 33193734, 2020). "In GBM and other cancer models, MSI1 was reported to promote a stem-like cell state by modulating self-renewal, migration/invasion, differentiation, chemoresistance and recurrence." (PMID 33291443, 2020). "Although studies have shown that targeting MSI1 inhibits cancer growth, drugging the protein to inhibit its function in cancers remains a challenge as RNA-binding proteins are not enzymes, which have traditional catalytic pockets for inhibition." (PMID 31824472, 2019). "Our previous study identified (−)-gossypol as a small molecule inhibitor of MSI1 that reduced cancer cell proliferation and xenograft growth." (PMID 30097032, 2018). "Inhibiting MSI1 is a promising therapeutic strategy for preventing cancer cell proliferation and progression." (PMID 30097032, 2018). "For example, Msi-1 and Msi-2 are overexpressed in a number of human carcinomas (cancers of epithelial origin), but downregulated in others (rev." (PMID 29535610, 2018). "Robust pro-inflammatory studies have revealed that IL-6 intermediates the AKT/PI3K pathway in contribution to cancer cell survival, but the connection with MSI1 remain uncertain." (PMID 27285760, 2016). "In fact, MSI1 secures the cells from apoptotic process, and in part, increases the growth of cancer cells and clonogenic ability." (PMID 27285760, 2016).